HNF4A (hepatocyte nuclear factor 4 alpha)
Diseases named in the same sentence as HNF4A in open-access papers (continued):
Sharing a sentence is not in itself a finding about the gene and the disease.
MODY (continued). "Notable examples include HNF4α gene therapy, which seeks to restore insulin secretion in MODY by correcting mutations in the HNF4α gene, crucial for pancreatic β-cell function." (PMID 40926269, 2025). "Among the different forms of MODY, HNF4A-MODY (MODY1) is caused by mutations in the HNF4A gene, which encodes a transcription factor essential for glucose metabolism." (PMID 40486195, 2025). "Prolonged follow-up of this patient indicated a gradual decline in pancreatic function associated with HNF4A-MODY." (PMID 40589512, 2025). "A separate study analyzing a panel of 14 MODY-associated genes in 178 patients with a MODY phenotype from Western Siberia identified mutations in HNF4A, GCK, HNF1A, and ABCC8 genes in 38 patients." (PMID 39859454, 2025). "In summary, we have identified a novel de novo heterozygous missense mutation in the HNF4A gene in a Chinese patient diagnosed with MODY." (PMID 40589512, 2025). "The most prevalent forms of MODY in individuals with mutations in the HNF4A and HNF1A genes are specified by specific beta-cell dysfunction." (PMID 39902162, 2024). "Pathogenic variants in the glucokinase gene (GCK‐MODY), in hepatocyte nuclear factor 1‐alpha (HNF1A‐MODY), and HNF4A are the most common causes, accounting for >90% of all MODY types in the UK, Europe, and the United States." (PMID 39511990, 2024). "Here, we describe a Japanese patient with MODY with a heterozygous HNF4A variant (c.742G > T, p.Asp248Tyr) inherited in an autosomal-dominant manner from her father." (PMID 38745825, 2024). "The phenotype of variant carriers and the segregation pattern (Family 14) suggest that the variant leads to HNF4A-MODY with reduced penetrance in addition to a delayed onset of disease and not being a risk factor for type 2 diabetes development." (PMID 38855865, 2024). "This study identified the I159T, W179C, and D260N mutations in HNF4A that co-segregated with the diabetic phenotype in three suspected MODY pedigree cases, broadening the spectrum of MODY1-associated HNF4A mutations." (PMID 37711893, 2023). "HNF4A/MODY1 mutations are frequently identified in Caucasian populations, accounting for an estimated 5% of MODY cases, whereas HNF4A mutations are rarely reported in Han Chinese families." (PMID 37711893, 2023). "Three heterozygous missense mutations in the HNF4A gene, I159T, W179C, and D260N, were identified in the probands of three unrelated MODY families using WES, one of which (W179C) was novel." (PMID 37711893, 2023). "The nonsense variant p.(Arg163Ter) was described by Lindner and coworkers (1997) as the second variant found in the HNF4A associated to MODY in a family from German ancestry." (PMID 35592779, 2022). "LOF mutations in HNF1A, HNF1B and HNF4A, all leading to defective insulin secretion and reduced β-cells mass, cause some forms of MODY possibly associated with kidney and/or liver abnormalities." (PMID 35052457, 2022). "Mutations in HNF1A and HNF4A are the most frequently identified aetiologies of MODY, and combined, account for 62% of MODY cases, typically characterized by dysfunctional pancreatic β cells with accompanying liver and/or kidneys defects." (PMID 36361703, 2022). "HNF4A-MODY is present in 5%–10% of MODY patients, and is caused by more than 103 mutations identified in 173 families." (PMID 36361703, 2022). "More than 75% of MODY cases are the outcome of mutations in four genes [Hepatocyte Nuclear Factor (HNF) 4 Alpha (HNF4A), HNF1A, HNF 1 Beta (HNF1B), and glucokinase (GCK)] but their frequency varies among tested populations." (PMID 34393998, 2021). "We identified a total of 22 missense variants (3 novel variants) in 27 patients (60.0%) in the GCK, HNF4α, and HNF1α genes in this study involving a small set of 45 Japanese pediatric MODY patients." (PMID 34746319, 2021). "Till 2013, 103 different mutations were reported in 173 families, whereas currently there are around 180 mutations in HNF4A associated with MODY (ClinVar)." (PMID 34299172, 2021).
MODY (continued). "R85W is a mutation within the DNA-binding domain of HNF4A that was repeatedly identified in MODY patients." (PMID 34732735, 2021). "In humans, mutations in the HNF4α gene cause maturity-onset diabetes of the young (MODY), and the elevated activity of this protein has been associated with gastrointestinal cancers." (PMID 33114319, 2020). "Mutations in glucokinase (GCK), hepatocyte nuclear factor-1 homeobox A (HNF1A), and hepatocyte nuclear factor-4 homeobox A (HNF4A) are the most common causes of MODY." (PMID 32528556, 2020). "Mutations within the HNF4α gene cause the heritable form of type 2 diabetes, maturity-onset diabetes of the young 1 (MODY-1), highlighting the receptor’s crucial role in metabolic homeostasis." (PMID 33114319, 2020). "It was found that individuals with MODY carrying mutations in the HNF1A or HNF4A genes are sensitive to low-dose sulfonylureas, though the mechanism is incompletely understood." (PMID 28447115, 2017). "HNF4A is one of the most commonly mutated and important causative genes for MODY, with more than 33 mutations being reported." (PMID 26981542, 2016). "As a liver-enriched transcription factor, HNF4α is also expressed in the kidney, small intestine, colon, stomach, and pancreas in which the mutation of HNF4A gene causes maturity-onset diabetes of the young in humans (MODY)." (PMID 24427299, 2014). "We describe, for the first time, the gradual alteration in glucose homeostasis and development of MODY in the HNF4A-mutation carrier after resolution of hyperinsulinaemic hypoglycaemia, on prospective follow-up with an annual oral glucose tolerance test." (PMID 24299156, 2014). "Heterozygous mutations in the genes encoding the glycolytic enzyme glucokinase and the transcription factors, HNF-1α, HNF-4α and HNF1β have been shown to cause MODY." (PMID 24299156, 2014). "HNF1A and HNF4A mutations cause a similar clinical phenotype of MODY, characterized by progressive beta-cell dysfunction, defects in glucose-stimulated insulin secretion and sensitivity to low-dose sulphonylureas." (PMID 23803251, 2013). "Testing for HNF4A mutations is recommended when HNF1A genetic analysis does not show a mutation in individuals with clinical features of MODY or in diabetic family members with macrosomia or diazoxide-responsive neonatal hyperinsulinism." (PMID 23803251, 2013). "Several mutations have been identified from MODY patients and previous studies on their mutational effects have shown that subtle disruptions of HNF4α’s molecular function can cause significant effects in afflicted MODY patients." (PMID 22952853, 2012). "MODY is a disease caused by mutations in autosomal dominant genes: MODY1–5 result from mutations in Hnf4α, glucokinase, Hnf1α, Pdx1, and Tcf2, respectively." (PMID 21829703, 2011). "Mutations in the HNF4A gene are documented dominantly inherited maturity onset diabetes of the young (MODY)." (PMID 20806066, 2010). "The aim of the present study was to determine the prevalence and nature of mutations in HNF4α gene in Iranian patients with a clinical diagnosis of MODY and their family members." (PMID 20003313, 2009). "In summary, Val/Met255 mutation in the HNF4α gene was identified in about one fourth of Iranian families affected with MODY." (PMID 20003313, 2009). "Some missense mutations in the HNF4α gene have been shown to segregate with diabetes in MODY pedigrees in different populations." (PMID 20003313, 2009). "Here, it is indicated that the prevalence of HNF4α mutation among Iranian patients with clinical MODY is considerable." (PMID 20003313, 2009). "Hepatocyte Nuclear Factor 4 Alpha (HNF4A)-related maturity-onset diabetes of the young (MODY) constitutes approximately 5% to 10% of all MODY cases; however, the literature documents only around 20 instances of HNF4A-MODY in China." (PMID 40589512, 2025). "Furthermore, patients with MODY with the HNF4A (Q268X) mutation have decreased plasma Lp(a) concentrations." (PMID 40370778, 2025).
MODY (continued). "Pathogenic variants in HNF4A are commonly associated with MODY." (PMID 40149950, 2025). "As GCK, HNF1A, and HNF4A variants make up almost 80% of all MODY cases, it may be prudent to test for these first." (PMID 39717432, 2025). "Many cases of MIDY and MODY require insulin therapy, however, MODY 1 and MODY 3, caused by mutations in the transcription factors hepatocyte nuclear factor 4α (HNF4A) and 1α (HNF1A), respectively, can often improve insulin secretion with sulfonylurea treatment." (PMID 40666490, 2025). "Although pathogenic HNF4A variants are commonly associated with maturity-onset diabetes of the young (MODY1; HNF4A-MODY), rare phenotypes also include hyperinsulinemic hypoglycemia, renal Fanconi syndrome and liver disease." (PMID 38433330, 2024). "When there is a family history suggestive of maturity-onset diabetes of the young (MODY), genetic testing for HNF1A and HNF4A should be considered because these conditions can cause transient hyperinsulinism in the newborn period." (PMID 37454648, 2024). "However, mutations in HNF1A, GCK, and HNF4A are the most common causes of MODY, accounting collectively for 85–90% of all cases." (PMID 39408828, 2024). "Additionally, mutation of HNF4α in people is associated with MODY (maturity onset diabetes of the young;), further demonstrating its crucial contribution to glucose homeostasis." (PMID 38731997, 2024). "Therefore, regular screening for retinopathy and nephropathy in individuals with MODY, especially with variants in HNF4A, HNF1A, and HNF1B, is recommended." (PMID 39511990, 2024). "Mutations in GCK, HNF1A, HNF1B, and HNF4A account for approximately 80% of the MODY cases." (PMID 37941991, 2023). "Fewer than 20 HNF4A mutations have been described in the Chinese MODY pedigrees." (PMID 37711893, 2023). "HNF4A-MODY is caused by variants in the gene encoding hepatic nuclear factor 4 (HNF4α), a member of the nuclear hormone receptor superfamily and a transcription factor, which exhibits predominant expression in the liver, gastrointestinal tract, kidney, and pancreatic islets." (PMID 37711893, 2023). "Mutations in GCK, HNF1A and HNF4A are the most common causes of MODY." (PMID 34789499, 2022). "On the other, maturity onset diabetes of the young (MODY) is a monogenic disease where pathogenic mutations in specific genes (GCK, HNF1A, HNF4A, etc.)have been identified." (PMID 34668636, 2022). "Concerning the others MODY subtypes, we found one variant in each HNF4A, HNF1B, and MT-TL1." (PMID 35592779, 2022). "In people with MODY due to HNF4A mutations, early life hypoglycaemia due to insulin hypersecretion is also described, and may be sustained, while 7% of those deficient for HNF1A develop liver adenomatosis." (PMID 35618782, 2022). "Mutations in the HNF4A protein can cause juvenile-onset diabetes mellitus (MODY) and haemophilia." (PMID 35132353, 2022). "The most common transcription factors that cause MODY when mutated belong to the hepatocyte nuclear factor (HNF) family (HNF4A, HNF1A and HNF1B), resulting in MODY1, MODY3 and MODY5, respectively, but other causal transcription factor genes have also been described." (PMID 34440499, 2021). "Moreover, mutations in GCK, HNF1A, and HNF4A HNF1B are the most common causes of MODY, accounting for 32%, 52%, 10% and 6% of all infected patients in the UK, respectively." (PMID 34421822, 2021). "However, it has recently been found that higher birthweight is associated with reduced penetrance of HNF4A-MODY (unpublished data from J. Locke and K. Patel)." (PMID 33569631, 2021). "Heterozygous mutations in HNF4A are relatively rare and constitute 5–10% of all MODY cases." (PMID 34299172, 2021). "Alternatively, other genes implicated in the pathogenesis of MODY could be more frequent in these groups, such as HNF4A, insulin promoter factor-1 (IPF-1), HNF1B, NeuroD1 and others." (PMID 31576961, 2020). "The three most known forms of MODY are caused by modifications to the hnf4a, gck, and hnf1a genes." (PMID 32864159, 2020).
MODY (continued). "MODY are also associated with mutations in the genes encoding transcription factors like, hepatic nuclear factor 4 alpha (HNF4A), HNF1 homeobox A (HNF1A), pancreatic and duodenal homeobox 1 (PDX1), HNF1 homeobox B (HNF1B) and neurogenic differentiation 1 (NEUROD1)." (PMID 22399922, 2010). "Haploinsufficiency of HNF4α in man is responsible for maturity onset diabetes of the young type 1 (MODY1)." (PMID 19424486, 2009). "Moreover, for HNF1A and HNF4A, disruption of positive feedback and of cooperativity has been identified as the cause of MODY." (PMID 41356216, 2025). "Heterozygous missense mutations in the HNF4A gene (NM_175914.5), I159T (c.476T>C, p.Ile159Thr), W179C (c.537G>C, p.Trp179Cys), and D260N (c.778G>A, p.Asp260Asn), were identified in the probands of three unrelated MODY families, which co-segregated with hyperglycemic phenotypes in their families." (PMID 37711893, 2023). "However, heterozygous mutations in the GCK (glucokinase) (MODY 2), HNF1A (hepatocyte nuclear factor 1 alpha) (MODY 3), and HNF4A (hepatocyte nuclear factor 4 alpha) (MODY 1) genes are the most frequent, and together they explain over 95% of the known genetic causes of MODY." (PMID 31968686, 2020). "Therefore, people with mutations in HNF1A or HNF4A causing MODY can be managed with low-dose sulphonylurea therapy, and those misdiagnosed may therefore potentially stop insulin injections or have tablet regimens rationalised." (PMID 30377832, 2018). "Of these cases, 80% are contributed by variants in common genes associated with maturity‐onset diabetes of the young (MODY), including glucokinase (GCK), hepatic nuclear factor (HNF)‐1A, HNF1B and HNF4A." (PMID 40966384, 2025). "HNF4A-MODY should be considered a potential diagnosis in young diabetic patients, and genetic testing is essential for establishing an appropriate therapeutic approach." (PMID 40149950, 2025). "One patient with HNF4A-MODY was treated with sulfonylurea and metformin, and blood glucose control was good after 1 year of follow-up." (PMID 40303944, 2025). "Typically, low-dose sulfonylurea medications are effective in treating both HNF1A- and HNF4A-MODY patients, although other oral hypoglycemic agents have also been shown to improve blood glucose control." (PMID 40149950, 2025). "HNF4A-MODY accounts for approximately 5% to 10% of all MODY cases; however, it is infrequently observed in the Chinese population." (PMID 40589512, 2025). "Future studies should gather further empirical evidence showing that MODY is caused by disrupted TF cooperativity or positive feedback (beyond HNF1A and HNF4A)." (PMID 41356216, 2025). "Following the diagnosis of HNF4A-MODY, the patient's treatment was switched from insulin to sulfonylureas, resulting in improved glycaemic control and time in range, along with an improved quality of life." (PMID 40486195, 2025). "Switching to GLP1RA treatment in HNF4A-MODY still yields a good effect after a prolonged disease course." (PMID 40589512, 2025). "Mutations at the HNF4α binding site of MED25 are often associated with MODY, underscoring the role of MED25 in the HNF4α-mediated insulin secretion and associated diabetes." (PMID 40940746, 2025). "Among the confirmed MODY genes, mutations in HNF1A, GCK, and HNF4A remain the most common, collectively accounting for approximately 90% of all genetically confirmed cases." (PMID 41367630, 2025). "Many MODY-associated TF genes show incomplete penetrance, e.g., HNF1A, HNF1B, HNF4A, NEUROD1, PDX1, and RFX6." (PMID 41356216, 2025). "Our findings align with those of a study of 224 MODY patients in Turkey, where mutations were identified in the following proportions: 65% in the GCK gene, 19% in HNF1A, 3.6% in HNF4A, 3.6% in KLF11, and 3.1% in HNF1B." (PMID 39859454, 2025). "Thirteen MODY subtypes have been identified so far, with HNF1A, HNF4A, and GCK mutations accounting for the majority of cases." (PMID 40777711, 2025).